KHK (ketohexokinase)
Diseases named in the same sentence as KHK in open-access papers (continued):
Sharing a sentence is not in itself a finding about the gene and the disease.
hyperuricemia (2 papers, 2021 to 2022). An abnormally high level of uric acid. "Furthermore, fructose has a significant role in hyperuricemia through increased activity of ketohexokinase (KHK) on adenosine monophosphate (AMP) degradation and induction of increased serum lactate which then competes with uric acid for excretion by the kidney." (PMID 36247176, 2022).
liver disease (2 papers, 2025). "Here we investigated whether alcohol preference and alcohol-associated liver disease (ALD) are mediated through fructose metabolism by ketohexokinase (KHK)-A/C." (PMID 41214144, 2025). "KHK: ketohexokinase, MASLD: metabolic dysfunction-associated steatotic liver disease." (PMID 40130107, 2025).
non-alcoholic steatohepatitis (2 papers, 2021 to 2023). "Given the fact that existing inhibitors targeting KHK have been tested in clinical trials for nonalcoholic steatohepatitis (NASH), it would be of interest to analyze their effects as adjuvant therapies on PDAC patients." (PMID 37559908, 2023). "Mice provided with a 30% fructose solution to drink for 10 weeks as well as obese human subjects with non-alcoholic steatohepatitis (NASH) showed increased hepatic expression of KHK and downstream lipogenic genes Acaca, Acly and Scd1." (PMID 33923531, 2021).
alcoholic liver diseases (1 paper, 2023). A disorder caused by damage to the liver parenchyma due to alcohol consumption. "We present here evidence that in aldolase B KO mice, the metabolism of non-dietary fructose via KHK could represent a novel and important step in the pathogenesis of alcoholic liver disease as well." (PMID 37892451, 2023).
cervical cancer (1 paper, 2025). A primary or metastatic malignant neoplasm involving the cervix. "In cervical cancer, NAT10/ac4C/FOXP1 induced the expression of GLUT4 and KHK, thereby promoting glycolytic metabolism and immune suppression." (PMID 39143228, 2025).
colorectal adenoma (1 paper, 2020). An adenoma that arises from the colon or rectum. "Elevated KHK protein levels have also been detected in human colorectal adenomas compared to normal colon tissue." (PMID 32733884, 2020).
deficiency (1 paper, 2020). "Essential fructosuria (OMIM 229800) is a benign condition resulting from KHK deficiency." (PMID 32733884, 2020).
essential fructosuria (1 paper, 2021). Essential fructosuria is a rare autosomal recessive disorder of fructose metabolism caused by a deficiency of fructokinaseenzyme activity. "Essential fructosuria (EF) (OMIM #229800) is an autosomal recessive condition caused by loss-of-function variants in the ketohexokinase (KHK) gene (HGNC:6315) and characterized by intermittent appearance of fructose in the urine." (PMID 33621267, 2021). "Essential fructosuria (EF) is a benign, asymptomatic, autosomal recessive condition caused by loss-of-function variants in the ketohexokinase gene and characterized by intermittent appearance of fructose in the urine." (PMID 33621267, 2021).
Failure to thrive (1 paper, 2023). Failure to thrive (FTT) refers to a child whose physical growth is substantially below the norm. "In consequence, the metabolism of endogenous fructose by KHK results in a marked accumulation of F1P, causing metabolic dysregulation, liver dysfunction and injury and failure to thrive." (PMID 37892451, 2023).
Hypoglycemia (1 paper, 2023). A decreased concentration of glucose in the blood. "Gene deletion of ketohexokinase (Khk), an enzyme upstream of Aldob, is sufficient to prevent hypoglycemia and liver and intestinal injury associated with feeding Aldob−/− mice fructose." (PMID 37049617, 2023).
kidney cancer (1 paper, 2024). Primary or metastatic malignant neoplasm involving the kidney. "These organ-specific expression patterns call for a reexamination of KHK's role in blood, lung, liver, brain, uterus, and kidney cancers to determine whether KHK-A is a potential target for preventing cancer metastasis." (PMID 38971308, 2024).
lipidosis (1 paper, 2023). "In addition, endogenous fructose production via the polyol pathway has also received attention; gene deletion of aldose reductase (Ar), ketohexokinase (Khk), and triokinase (Tkfc) has been found to prevent the development of fructose-induced liver lipidosis." (PMID 37049617, 2023).
lung carcinoma (1 paper, 2022). "While low to no protein detection of DET1 and KHK were observed in both normal and lung cancer tissue." (PMID 36194576, 2022).
pancreatic carcinoma (1 paper, 2023). "To determine the expression of KHK in biopsies of patients with pancreatic carcinoma we performed immunohistochemical analysis (IHC) of tissue sections of human tumor and adjacent non-tumor pancreatic tissues in 42 cases." (PMID 37559908, 2023). "We demonstrate that KHK is upregulated in pancreatic cancer and show that genetic ablation of KHKC is sufficient to delay the onset and the development of PDAC KPC-driven PDAC in vivo by downregulating MAPK and mTOR signaling." (PMID 37559908, 2023). "To investigate the function of KHK and fructose diet in pancreatic cancer development, we first treated mouse-derived organoids with either high (17.3 mM) or low (3 mM) glucose, or low glucose plus high fructose (1 mM)." (PMID 37559908, 2023). "In this study, we dissected the role of different KHK isoforms and fructose metabolism in the development and progression of pancreatic cancer." (PMID 37559908, 2023). "Our data provide new insights into the role of KHK in PDAC progression and imply that inhibiting KHK could have profound implications for pancreatic cancer therapy." (PMID 37559908, 2023). "Here, we show that KHK expression is induced in human PDAC tissue sections and in mouse KPC tumors that fully recapitulate pancreatic cancer." (PMID 37559908, 2023).
peroxisomal disorders (1 paper, 2020). "Thus, it would be important to examine whether expression and activity of fructolytic enzymes are also reduced in humans with peroxisomal disorders or whether inhibiting KHK activity would improve clinical prognosis." (PMID 32733884, 2020).
senile cataract (1 paper, 2024). A cataract with no obvious cause occurring in persons over 50 years old. "After correction for multiple testing, we identified two potential causal genes, namely KHK associated with senile cataract (OR = 1.089, 95%CI (1.035–1.145), FDR.p = 1.44 × 10−3) and CFHR1 (OR = 3.049, 95%CI (2.636–3.527), FDR.p = 7.04 × 10−50)." (PMID 39408566, 2024).
Zellweger syndrome (1 paper, 2020). "We observed a considerable decrease in KHK expression followed by ALDOB, both enzymes unique for fructose metabolism, on mRNA and protein levels in a Zellweger syndrome mouse model (Pex2–/– mice)." (PMID 32733884, 2020). "We demonstrate a strong decrease in total KHK at the mRNA and protein level, which is also reflected in decreased expression of both the Khka and Khkc isoforms, in livers from the Pex2–/– mouse model for Zellweger syndrome without functional peroxisomes." (PMID 32733884, 2020).
cancer (18 papers, 2017 to 2025). A tumor composed of atypical neoplastic, often pleomorphic cells that invade other tissues. "Insights into fructose's contribution to cancer cell metabolism emphasize its role in promoting cell survival, particularly via pathways that involve ketohexokinase (KHK) and aldolase B (ALDOB)." (PMID 40520908, 2025). "In HCC, reduced expression of KHK impairs fructose metabolic functions, detectable by hyperpolarized magnetic resonance spectroscopy in vivo, potentially offering new biomarkers for cancer diagnosis and monitoring." (PMID 40520908, 2025). "Fructose metabolism is increasingly recognized as a critical pathway in cancer metabolism, with KHK acting as a central enzyme in these processes." (PMID 40520908, 2025). "Multiple studies indicate that GLUT5, together with KHK, plays a crucial role in fructose metabolism; importantly, altered GLUT5 activity disrupts cellular carbohydrate metabolism and thereby elevates cancer risk, directly contributing to carcinogenesis." (PMID 40520908, 2025). "Protein–protein interactome analysis indicated distinct expression patterns and downregulation of partner proteins in different tumor tissues, warranting a reevaluation of KHK’s role in cancer development and progression." (PMID 38971308, 2024). "The connections between different cancer genes and the KHK signaling pathway suggest that KHK is a potential target for preventing cancer metastasis." (PMID 38971308, 2024). "High dietary fructose intake upregulates KHK activity in the brain, further supporting the enzyme’s role in fructose metabolism and possibly cancer." (PMID 39107723, 2024). "Recent reports suggest that knocking down fructose metabolism by deleting KHK suppresses cancer growth in response to HFCS in APC mice." (PMID 37559908, 2023). "Loss of KHK function is associated with neoplastic disease, as lower KHK transcript levels or reduced KHK enzymatic activity has been reported in most cancers." (PMID 37559908, 2023). "To examine the role of KHK in this process, we measured the cellular levels of two KHK isoforms in various cancer cell lines." (PMID 33116123, 2020). "Because KHK is the first step in fructolysis, biochemical and structural characterization of its isozymes is important for addressing knowledge gaps and opening potential new avenues to effective therapies for the chronic effects of obesity, cancer, and MetS." (PMID 38971308, 2024). "Importantly, knocking down fructokinase (ketohexokinase), the first enzyme involved in fructose metabolism, was found to suppress cancer growth in response to HFCS." (PMID 32670573, 2020). "Many cancer cells overexpress KHK, and essential fructosuria, the genetic disorder caused by a loss of function mutation in KHK, is clinically asymptomatic and harmless, further supporting the notion that clinical inhibition of KHK may be tolerated in cancer patients." (PMID 33302403, 2020). "Although less directly involved in fructose metabolism than KHK, HK2’s broad role in phosphorylating hexose sugars underscores its significance in cancer cell metabolism and survival." (PMID 39107723, 2024). "To investigate the mechanisms by which KHK and its isoforms influence PDAC development, we performed RNA seq from sorted Epcam+; CD45– cancer cells of age-matched KPC mouse tumors and from tumors with genetic ablation of KhkC, KhkA and KhkA/C." (PMID 37559908, 2023). "Here, increased SORD activity in adenomas and cancer cell lines lead to changes in expression of AKR1B1 and KHK." (PMID 33302403, 2020). "Alternative splicing of Bcl-2 family genes Mcl-1 and Bcl-x, a-raf gene, fructokinase (KHK) gene, RON gene, and EWS-FLI1 transcripts by hnRNP F/H are reported to contribute to various cancer cells proliferation, metastasis, and apoptosis-resistance." (PMID 31863069, 2020).
cancer (continued). "To ascertain whether the intracellular catabolism of fructose was required for cancer cell proliferation, we determined the effects of GLUT5 and KHK on cell proliferation promoted by fructose using shRNA to knockdown GLUT5 or KHK." (PMID 28970966, 2017). "However, studies investigating the cell autonomous impact of different KHK-isoforms on cancer cells in connection with fructose metabolism are lacking." (PMID 37559908, 2023).
tumor (13 papers, 2019 to 2025). "KHK expression in several tumor cells is abnormally high, and fructose can drive tumor growth and metastasis through the activity of KHK." (PMID 40549205, 2025). "We assessed bioluminescence emissions of the excised livers and intestines and found that AKR1B1-induced tumor metastasis was almost completely attenuated by KHK knockdown." (PMID 38200154, 2024). "KHK has been described as a rate-limiting enzyme for fructose metabolism in tumor and normal tissue." (PMID 33762003, 2021). "Endogenous fructose production coupled with KHK, which is commonly highly expressed in tumors, bypasses the rate-limiting step in glycolysis and rapidly meets the energy and substrate requirements of tumor cell growth, thereby promoting tumor cell growth." (PMID 40549205, 2025). "Moreover, SiHa tumor xenografts established from cells with NAT10 deficiency showed significantly decreased staining for NAT10, FOXP1, GLUT4, and KHK." (PMID 37818745, 2023). "Ingestion of high-fructose corn syrup could enhance colon tumorigenesis via the action of ketohexokinase, a fructose-converting enzyme that changes the tumor cell metabolism to increase the production of fatty acids needed for tumor growth." (PMID 33364203, 2020). "Fructose metabolism, particularly through key enzymes such as ketohexokinase (KHK) and aldolase B (ALDOB), along with the fructose transporter GLUT5, supports tumor growth, metastasis, and therapeutic resistance." (PMID 40520908, 2025). "Consistent with the observations in mouse tumors, epithelial KPC tumor organoids exhibited higher GLUT5, KHK, ALDOB protein levels, and higher activity of KHK compared to the normal KP organoids." (PMID 37559908, 2023). "We provide evidence that the fructolytic proteins Glut5, KHK, and HK2 are all expressed in two endothelial cell lines, and that fructose can be absorbed and metabolized by these cells and contribute to tumor angiogenesis." (PMID 37507736, 2023). "The metabolism-reprogramming marker ketohexokinase (KHK)-A and acetyl-CoA synthetase 2 (ACSS2) phosphorylation at S659 (ACSS2 pS659) play important roles in tumorigenesis and tumor development." (PMID 31750240, 2019). "In HCC, tumor endothelial cells enhanced fructose metabolism by upregulating SLC2A5 and KHK, thereby activating the AMPK signaling pathway and mitochondrial function, enhancing endothelial cell function, and exacerbating tumor angiogenesis, growth, and metastasis." (PMID 40520908, 2025). "While the majority of tumor tissues stained positive for KHK, the adjacent non-tumor pancreatic tissues displayed low or no positivity." (PMID 37559908, 2023).
metabolic disease (7 papers, 2023 to 2025). A congenital disorder (due to inherited enzyme abnormality) or acquired (due to failure of a metabolically important organ) disorder resulting from an abnormal metabolic process. "KHK is essential to fructose metabolism, and its overactivity has been linked to metabolic diseases, including MASLD." (PMID 40130107, 2025). "Genetic ablation of A1cf markedly reduced the expression of the KHK-C isoform and protected mice from fructose-induced metabolic disease, thereby phenocopying KHK deficiency." (PMID 37937648, 2023). "The inhibition of KHK, particularly KHK-C, is considered a potential strategy for mitigating the adverse effects of excessive fructose consumption, which is linked to these metabolic disorders." (PMID 39452863, 2024). "The comparison of compounds based on their LibDock Scores reveals that compound 60151560, with a score of 162.98, is the most promising KHK-targeting compound for metabolic diseases such as MASLD." (PMID 40130107, 2025). "The importance of KHK for fructose-related metabolic diseases has promoted the development of KHK inhibitors that are now being assessed in clinical trials." (PMID 39452863, 2024). "This further suggests that KHK‐mediated fructose metabolism is critical for fructose‐induced metabolic diseases." (PMID 38344397, 2024). "KHK is a critical enzyme in fructose metabolism, and its inhibition could be a potential therapeutic target for treating diet-induced metabolic disorders." (PMID 40573122, 2025). "Understanding KHK's role in fructose metabolism and its implications for MASLD underscores the importance of dietary interventions and lifestyle modifications in the prevention and management of metabolic diseases." (PMID 40130107, 2025). "Therefore, inhibition of KHK has therapeutic implications for NAFLD, NASH, T2D, and other fructose‐mediated metabolic diseases." (PMID 38344397, 2024).
heart disease (1 paper, 2023). "Thus, the activation of KHK and HIF-1α are likely critical factors contributing to mediating heart disease in this condition." (PMID 37237888, 2023).
infection (1 paper, 2023). The state of being infected such as from the introduction of a foreign agent such as serum, vaccine, antigenic substance or organism. "The infection efficiency of AAV in the hippocampus was confirmed by the expression of EGFP, and KHK expression was efficiently knocked down by shRNA." (PMID 37907746, 2023).
kidney disease (1 paper, 2023). "Third, in KHK-KO pound mice, the development of kidney disease and early mortality was prevented despite the mice still gaining excess weight." (PMID 37238651, 2023). "Another limitation is that our study does not elucidate the site or organ where fructose metabolism is important to accelerate kidney disease in obese mice and the specific isoform of KHK involved in the process." (PMID 37238651, 2023).
KHK also shares sentences with these, for which no sentence is quoted: cardiovascular disease (2 papers); fructose intolerance (2); kidney damage (2); asthma (1); brain disorder (1); Cerebral ischemia (1); dementia (1); diabetic nephropathy (1); fructose metabolic disorders (1); genetic disorder (1); hepatocellular carcinoma (1); Hyperinsulinemia (1); hyperlipidemia (1); hypertriglyceridemia (1); lactic acidosis (1); liver (1); liver cancer (1); lung disease (1).